SFPQ (splicing factor proline and glutamine rich)
Diseases named in the same sentence as SFPQ in open-access papers (continued):
Sharing a sentence is not in itself a finding about the gene and the disease.
leukemia (1 paper, 2024). A malignant (clonal) hematologic disorder, involving hematopoietic stem cells and characterized by the presence of primitive or atypical myeloid or lymphoid cells in the bone marrow and the blood. "Most of these are recurrent and class-defining in pAML (for example, KMT2Ar, 20.3%; RUNX1::RUNX1T1, 12.4%), whereas we also found fusions recurrent in other leukemias, such as SET::NUP214 (n = 1) or SFPQ::ZFP36L2 (n = 1)." (PMID 38212634, 2024).
motor neuron diseases (1 paper, 2016). "PSF/SFPQ mislocalized from the neuronal nucleus to the cytoplasm in the motor neuron diseases ALS and FTLD, which were caused by TDP-43 mutations." (PMID 27034888, 2016).
Obesity (1 paper, 2021). Accumulation of substantial excess body fat. "NONO is an RNA binding protein that forms a heterodimer with SFPQ, a splicing factor that has been shown to be decreased in obesity." (PMID 33716968, 2021). "The decreased expression of SFRS10, SFRS7, SF3A1, SFPQ and HNRPK in obese liver was further confirmed in a mouse model of diet-induced obesity." (PMID 33716968, 2021).
osteosarcoma (1 paper, 2020). A usually aggressive malignant bone-forming mesenchymal neoplasm, predominantly affecting adolescents and young adults.
poliovirus infection (1 paper, 2018). An disease or disorder caused by infection with Enterovirus C. "Since SFPQ is cleaved in the presence of a pan-caspase inhibitor and displays a differential cleavage pattern during HRV16 and poliovirus infection, it is likely to be a target of the viral proteinase 3CD/3C during infection." (PMID 30142213, 2018).
pulmonary diseases (1 paper, 2021). "This study demonstrates that SFPQ is a central player in regulating mutant F508del-CFTR in CF lung disease." (PMID 34404863, 2021). "Our findings provide new insights into SFPQ-mediated molecular mechanisms and point to possible novel epigenetic therapeutic targets for CF and related pulmonary diseases." (PMID 34404863, 2021). "Thus, multiple processes, in which SFPQ plays a central role, are operating in concert to regulate CF lung diseases, characterized by inflammation, fibrotic factor as well as lack of functional CFTR." (PMID 34404863, 2021).
renal carcinoma (1 paper, 2021). A carcinoma arising from the epithelium of the renal parenchyma or the renal pelvis. "Whereas in colorectal, lung and renal cancer SFPQ has been reported to act as a transcriptional repressor that serves to dampen proto-oncogene expression, a function that is frequently derailed via the overexpression and binding of oncogenic lncRNAs, such as MALAT-1 and SANT1." (PMID 34218270, 2021).
renal cell carcinoma (1 paper, 2024). "Although over the past 30 years, numerous fusion partners have been identified in TFE3-rearranged renal cell carcinoma and PEComa, ASPL/ASPSCR1, PRCC, SFPQ, NONO, and MED15 remain the most frequent in both groups of neoplasms." (PMID 39410016, 2024).
sarcoma (1 paper, 2023). A usually aggressive malignant neoplasm of the soft tissue or bone. "SFPQ, a specific DNA and RNA binding protein, is strictly related to neurodegenerative diseases because of its relationship with FUS protein (the neural homeostasis-binding fused in sarcoma)." (PMID 37446229, 2023).
Spinocerebellar ataxia (1 paper, 2023). "Interestingly, GPR125 and SFPQ were enriched in a neural signaling pathway in relation to Spinocerebellar ataxia." (PMID 36936424, 2023).
testis tumor (1 paper, 2020). "FGFR3, which has a role in testis tumor development might be coregulated by a different set, SFPQ, FXR2, and HNRNPA1, and all three bind it based on POSTAR2." (PMID 32316190, 2020).
ZIKV infection (1 paper, 2017). "ZIKV infection also results in downregulation of a splicing factor, SFPQ, which might result in impairment of neuronal development." (PMID 28112162, 2017).
cancer (35 papers, 2011 to 2025). A tumor composed of atypical neoplastic, often pleomorphic cells that invade other tissues. "Given a wide range of cellular activities, it is perhaps unsurprising that SFPQ has been implicated in several human diseases, including neurological disorders and cancer." (PMID 40276932, 2025). "SFPQ has been implicated in numerous cancers often due to interactions with coding and non-coding RNAs, along with some nuclear proteins." (PMID 37569873, 2023). "Studies of specific tyrosine kinases in cancer cell lines have also linked the phosphorylation of Y293 to a mislocalization of SFPQ to the cytoplasm." (PMID 30142213, 2018). "Considering this, elevated SFPQ level and the isoform location could serve as a cancer diagnostic and prognostic marker." (PMID 37569873, 2023). "Together, population-level in different cancer cell lines, and perturbation data argue for links between SFPQ and RAD51 expression." (PMID 40964404, 2025). "Most of the cancer cells were positive for SFPQ, which suggested that SFPQ was present on the cell surface." (PMID 40770831, 2025). "The observed dominant negative and lethal phenotypes associated with mutating the polymerization domain of both SFPQ and PSPC1 also indicate an essential role for this function in cancer cell survival." (PMID 40593584, 2025). "In cancer, SFpQ is frequently misregulated, overexpressed, or rearranged as part of oncogenic fusion events (e.g., SFPQ–TFE3) and its loss has been associated with altered splicing and genomic instability." (PMID 40964404, 2025). "SFPQ is a key component of paraspeckles; subnuclear condensates that regulate stress responses in viral infection, cancer, development, and neurodegeneration." (PMID 40964404, 2025). "Because SFPQ has multiple functions in cells, changes in its level should affect cell functions in cancer cells." (PMID 37569873, 2023). "SFPQ is an important protein in the maintenance of stem cell development and is also related to cancer proliferation and metastasis." (PMID 35707369, 2022). "In summary, our data shows that SFPQ not only regulates cancer cell proliferation, stemness, chemoresistance, invasion, and metastasis, but also serves as an upstream regulator of CD44v6." (PMID 35707369, 2022). "To test this, we explored if SFPQ expression was required for ‘cancer cell phenotypes’, in vitro, including increased cell growth, cell migration, EMT and decreased apoptosis and oxidative phosphorylation (OXPHOS)." (PMID 34218270, 2021). "Many molecules can facilitate proliferation, migration, and invasion of cancer cells by targeting SFPQ." (PMID 34760694, 2021). "The three transcription factors SFPQ, ZNF639 (also known as ZASC1) and PHF20 have been associated with cancer." (PMID 25089626, 2014). "We then examine if interacting cell surface SFPQ affects cancer cell function." (PMID 40770831, 2025). "Overexpression of SFPQ is essential for the malignancy of cancer cells." (PMID 40770831, 2025). "Moreover, recent research has identified SFPQ as a novel regulator of TGF-β signaling in cancer cells." (PMID 39757214, 2025). "Still the most direct involvement in cancer comes from Xp11.2 translocation renal cell carcinoma (XP11.2 tRCC) in which SFPQ is the fusion partner of MiT (microphthalmia transcription factor) family member gene, transcription factor binding to IGHM enhancer 3 (TFE3)." (PMID 40276932, 2025). "The current findings are based on a small number of patients with advanced cancers; however, with more human patient samples, the relationship between SFPQ levels and SFPQ isoform subcellular levels and cancer stages could be established." (PMID 37569873, 2023). "The cytoplasm isoform is another potential mechanism for SFPQ in cancer pathology." (PMID 37569873, 2023). "SFPQ could bind RNA, and RNA binding of its abnormal cytoplasm isoform might play roles in cancer cells too." (PMID 37569873, 2023).
cancer (continued). "Additionally, both IHC and IF also found that in the cytoplasm, SFPQ isoform is elevated in cancer cells." (PMID 37569873, 2023). "Both RACK1 and SFPQ regulate numerous cancer-related cellular processes." (PMID 35552415, 2022). "Several studies have indicated that SFPQ is involved in cancer cell invasion and metastasis." (PMID 35707369, 2022). "Since SFPQ plays a key role in RNA splicing, which is important for protein processing, we assume it might promote cancer progression via regulating RNA splicing." (PMID 35707369, 2022). "The impact of SFPQ knockdown on viable cell growth, cell death and cell migration was then determined and in each case, we observed a significant shift away from a cancer cell phenotype." (PMID 34218270, 2021). "The precise role of SFPQ in cancer is complex and appears to be tissue specific." (PMID 34218270, 2021). "Anti‐SFPQ antibodies could inhibit cancer cell proliferation and invasion by binding to SFPQ cells." (PMID 40770831, 2025). "Furthermore, the cytoplasmic isoform of SFPQ is only found in advanced cancers." (PMID 37569873, 2023). "In addition, SFPQ interacts with long non-coding RNAs in several cancer tissues." (PMID 28743736, 2017). "Therefore, we speculate that allosteric modulation of SFPQ amongst other factors may affect its DNA-binding capacity in cancer cells, and changes in SFPQ expression are a critical means of regulating PDE3A expression." (PMID 28743736, 2017). "Furthermore, studies in a cancer cell line identified SFPQ as a tumor suppressor suggesting that an altered distribution and depletion from nuclei could affect transcription of target genes." (PMID 22558197, 2012). "This study demonstrates that splicing factor proline and glutamine rich (SFPQ) is present on the cell surface in cancer cells, where it interacts with S100A4 and so forth proteins to alter cell function when SFPQ is a nuclear protein normally." (PMID 40770831, 2025). "Exploring the potential roles of SFPQ, DDX39B, and UBAP2 in other cancer types will also provide more information for developing precise treatment strategies." (PMID 39133261, 2024). "IIPA found that SFPQ interacts with many important proteins, such as YY1, RTN4, RICTOR, HDACs, BMI1, and HNRNPC, which are important in the development of cancer." (PMID 35707369, 2022). "Alternatively, in 9 non-cancer tissues, the cytoplasm was negative for SFPQ N-terminal antibody (short SFPQ) (Con: IPF: Cancer = 0.134 + 0.0115:0.17 + 0.024:2.56 + 0.23), indicating SFPQ isoforms are located differentially into subcellular compartments." (PMID 37569873, 2023). "The observations that SFPQ is highly expressed in primary EOC human samples and that its expression increased in samples from PT-exposed and PT-Res patients, support the possibility that SFPQ plays a role during cancer progression." (PMID 32332923, 2020). "This identifies SFPQ as a novel repressor of telomere recombination in both, telomerase-positive and telomerase-negative human cancer cells." (PMID 30824709, 2019). "Altogether, our data highlight a role for NONO and SFPQ in controlling RNA:DNA-hybrid-related telomere instability and telomere length homeostasis in both telomerase-positive and negative cancer cells." (PMID 30824709, 2019). "We thus conclude that NONO and SFPQ are novel regulators of telomere length in both telomerase-positive and negative cancer cells." (PMID 30824709, 2019). "We found that SFPQ/S100A4 formed a complex in those cancer cells but not in normal bronchial cells." (PMID 40770831, 2025). "Such a model supports the growing body of evidence of NonO and possibly SFPQ upregulation in different cancer cell types and clinical samples, suggesting that NonO might represent a potential therapeutic target." (PMID 38248868, 2024).
cancer (continued). "Panel A and B in S4 Fig, this complex network–‘Cancer, cell death and survival, injury and abnormalities’–is composed of several proteins, such as ribosomal 40S subunit, NF-κB complex, nucleophosmin (NPM1), and splicing factor, proline- and glutamine-rich (SFPQ)." (PMID 29481576, 2018). "Here, we show that NONO and SFPQ are novel telomere repeat associated proteins that collaborate to suppress RNA:DNA-hybrid-related replicative stress, telomere fragility and telomere recombination in both U-2 OS ALT cells and H1299 telomerase-positive human cancer cells." (PMID 30824709, 2019). "However, there are no studies of the molecular function of SFPQ in cancer tissues." (PMID 28743736, 2017). "In this review, we focus on several other established roles of NonO and SFPQ, including their participation in the cell cycle, nonhomologous end-joining (NHEJ), homologous recombination (HR), telomere stability, childhood birth defects and cancer." (PMID 38248868, 2024).
tumor (27 papers, 2007 to 2025). "In colorectal cancer, instead, MALAT1/NEAT2 triggers tumor growth and metastasis by binding to the splicing factor SFPQ causing the subsequent disruption of the splicing regulator complex SFPQ-PTBP2 and the release of the oncogene PTBP2." (PMID 33799493, 2021). "However, it is interesting to note that the most PM-specific SFPQ-lncRNA interactors included genes associated with tumour suppressor function, such as EMX2OS and FENDRR, whereas the most A2058-specific SFPQ-lncRNA interactors comprise genes widely reported as oncogenic, such as LINC00511." (PMID 34218270, 2021). "SFPQ and RAD51 expression were positively associated across tumor lineages (Pearson r = 0.625; p = 6.9×10−1 ), consistent with a model in which SFPQ supports RAD51 expression." (PMID 40964404, 2025). "SFPQ is a key nuclear protein regulator (Splicing Factor Proline and Glutamine Rich), which is overexpressed in tumors and functions to promote tumor cells proliferation, chemical resistance, and invasion." (PMID 36915153, 2023). "It has been reported that MALAT1 overexpression enhances cell proliferation and migration in vitro, and promotes tumor growth and metastasis in nude mice, due to tumor suppressor gene SFPQ and proto-oncogene PTBP2." (PMID 27888635, 2017). "Also, the interaction between PTBP2 and SFPQ regulated by MALAT‐1 RNA is known to promote tumor growth and metastasis." (PMID 34459124, 2021). "Additionally, the association of SFPQ, DDX39B, and UBAP2 with angiogenesis-related genes underscores their critical roles in tumor angiogenesis and progression, offering valuable insights for personalized treatment strategies and prognostic prediction in HCC and PRAD." (PMID 39133261, 2024). "In addition, the gene of SFPQ was also identified as tumor-related gene." (PMID 34760694, 2021). "Another study found that MALAT1 promotes tumour growth and metastasis in CRC by competitively binding to SFPQ (also known as Polypyrimidine Tract-Binding Protein-associated splicing factor) and releasing oncogene PTBP2 (polypyrimidine tract binding protein 2) from the SFPQ/PTBP2 complex." (PMID 31430887, 2019). "The deleted regions contained the tumour suppressors CDKN2C, SDHB, and SFPQ in 1p and CDKN2A in 9p in metastatic samples and the tumour suppressors BCL10 and NOTCH2 and the oncogenes JAK1 and NRAS in 1p in the non‐metastatic sample group." (PMID 37622176, 2023). "MALAT1 has been observed that interacts with SFPQ, releases PTBP2 from the SFPQ/PTBP2 complex (SFPQ-detached PTBP2), and accelerates tumor growth and metastasis." (PMID 35305641, 2022). "Furthermore, MALAT1 regulates proliferation, migration, and promotes tumor growth and metastasis in nude mice, this regulation could be through SFPQ and AKAP-9 as MALAT1 interact with SFPQ, hence releasing PTBP2 from the SFPQ/PTBP2 complex, facilitating cell proliferation and migration." (PMID 31632922, 2019). "Downregulation of SFPQ blocks TGF-β signaling, inhibiting tumor growth." (PMID 39796281, 2025). "Finally, the group mainly composed of NONO::TFE3 and SFPQ/PSF::TFE3 fusion neoplasms featured a low expression of angiogenesis modules and moderate enrichment of E2F signaling." (PMID 39410016, 2024).
neurodegenerative disease (11 papers, 2017 to 2025). A disorder of the central nervous system characterized by gradual and progressive loss of neural tissue and neurologic function. "SFPQ, as presented in this review, participates in the intricate network with many other known neurodegenerative disease-linked RBPs and tau." (PMID 32998269, 2020). "Many lines of evidence point to cytoplasmic accumulation of SFPQ as an emerging hallmark of neurodegenerative diseases." (PMID 32998269, 2020). "Importantly, several lines of evidence have demonstrated that SFPQ is implicated in neurodegenerative diseases, and it has been found to aberrantly translocate to the cytoplasm and form inclusions with SG proteins." (PMID 39636149, 2024). "The role of SFPQ, in concert with FUS, in maintaining the isoform ratio of tau, a primary component of neurofibrillary tangles in the neurodegenerative diseases, further interweaves the intricate network of SFPQ with other neurodegenerative disease-linked RBPs." (PMID 32998269, 2020). "In addition to neurodegenerative diseases, SFPQ is also associated with other neurodevelopmental disorders." (PMID 28392072, 2017). "Thus, further understanding of the precise mechanisms underpinning the interactions of SFPQ and other RBPs may also reveal the molecular mechanisms underlying the onset and progression of neurodegenerative diseases." (PMID 32998269, 2020). "For example, SFPQ has a critical role in the development and regulation of neurons such that the imbalanced nucleocytoplasmic distribution of SFPQ is an important factor in the neurodegenerative diseases ALS, FTLD and AD." (PMID 39698821, 2025). "In this review, we discuss recent findings on the roles of SFPQ with a particular focus on those in neuronal development and homeostasis as well as its implications in neurodegenerative diseases." (PMID 32998269, 2020). "We then discuss recent findings on the emerging role of SFPQ in neuronal function and homeostasis, in addition to its implications in neurodegenerative diseases." (PMID 32998269, 2020). "An increasing number of recent literature has also demonstrated the nuclear depletion and cytoplasmic aggregation of SFPQ in the neurodegenerative diseases including ALS, FTLD, and AD." (PMID 32998269, 2020). "Recent findings on the role of SFPQ and its implications in neurodegenerative diseases are reminiscent of TDP-43 in many ways." (PMID 32998269, 2020). "The elevated mRNA levels of SFPQ could also contribute directly to neurodegeneration: this excessive mRNA may sequester many proteins necessary for other cellular signalling, leading to translation defects among others, as has been noted for some other neurodegenerative disease associated proteins." (PMID 32577828, 2020). "Not surprisingly, the misregulation of SFPQ has been linked to pathological features shown by other neurodegenerative disease-associated RBPs such as aberrant RNA splicing, cytoplasmic mislocalization, and aggregation." (PMID 32998269, 2020). "While intron retention and SFPQ misregulation are hallmarks of ALS/FTLD, to date, transcriptopathy and intronic polyadenylation have not been associated with neurodegenerative disease." (PMID 36414621, 2022).